TLR5 (toll like receptor 5)
Diseases named in the same sentence as TLR5 in open-access papers (continued):
Sharing a sentence is not in itself a finding about the gene and the disease.
colitis (continued). "Compared with the other two groups, TLR5 and the potential transcription factor Sp3 were reduced in the epithelial cells of mice with DSS-induced colitis." (PMID 35893896, 2022). "But how can it be explained that a stronger intestinal TLR5 signaling, induced by a symbiotic commensal, correlates with beneficial effects during DSS-induced colitis accompanied by lower systemic cytokine levels?" (PMID 31206517, 2019). "In addition, the anti-IL10R induced colitis was not mediated by changes in the gut microbiome as the latter was altered in TLR5-deficient mice treated with anti- IL-10R whether or not they developed colitis." (PMID 30455704, 2018). "The specificity of our biomarker signature for the presence and types of intestinal inflammation was examined using two other mouse models of colitis (DSS-treated and TLR5−/− mice) and a model of extra-intestinal inflammation (CAIA)." (PMID 28566745, 2017). "PCoA yielded a different pattern of clustering between IL10−/− colitic mice (red, D98) and the other models of colitis [orange, DSS treated mice on day 7 (D7); and green, TLR5−/−]." (PMID 28566745, 2017). "Of the remaining miRNAs, miR-199a-3p was down-regulated in DSS induced colitis (and the IL10−/− model), but it was unaltered in the TLR5−/− model." (PMID 28566745, 2017). "Altogether, these results demonstrate DVF-induced exacerbation of DSS colitis was not mediated by TLR5 signaling." (PMID 38172943, 2024). "Previous study has reported that TLR5 is not required for flagellin-mediated exacerbation of DSS colitis." (PMID 38172943, 2024). "The SBP could reverse these changes, which indicated that TLR5 and its related inflammatory signaling pathway might play an essential role in TNBS-induced colitis." (PMID 35571126, 2022). "Our study provides a basis for understanding its essential role in goblet cell physiology and the healthy developmental architecture of the mucus layer by exploring the expression and function of TLR5, a key pattern recognition receptor, in TNBS-induced colitis." (PMID 35571126, 2022). "Dietary intake of βGl and βGh diminished colitis by the time-dependent modulation of autophagy and apoptosis, which involved TLRs (TLR4, TLR5) and Dectin-1 receptor activation, with βGI having a stronger effect on apoptosis (Caspase 3 expression) and βGh on autophagy (LC3B expression)." (PMID 33923129, 2021). "For example, E. coli flagellin enhances TLR5 signaling in intestinal DCs, leading to a higher expression of IL-22 and better maintenance of the intestinal barrier, to protect mice against DSS-induced colitis." (PMID 33381598, 2020). "Dependent on the housing conditions, Tlr5−/− mice either spontaneously develop a chronic form of colitis and/or metabolic syndrome or not." (PMID 31206517, 2019). "In IL-10−/− mice (not TLR5−/− mice), emulsifier-induced colitis correlated with enrichments in Biophila and Helicobacter, consistent with previous observations in IL-10−/− mice." (PMID 27531998, 2016). "However, the role of TLR5 in the pathogenesis of human IBD and murine colitis has been reported in the literature." (PMID 21203467, 2010). "Mechanistically, DVF could interact with LRRC19 (rather than TLR5) in colitis mice and organoids, and then induce the production of pro-inflammatory cytokines." (PMID 38172943, 2024). "In mice that exhibit spontaneous development of colitis, such as those lacking Toll-like receptors-5 (Tlr5−/−), IL-10 (Il-10−/−) or the transcription factor T-bet and the recombinase activating gene Rag (T-bet−/− x Rag2−/−), an increased intestinal level of Proteobacteria was reported." (PMID 32487227, 2020). "Administration of EcNΔfliC to DSS-treated Tlr5−/− mice did not positively affect the outcome of experimental colitis, as demonstrated by HCSs comparable to EcNΔfliC-treated WT mice and to DSS-only–treated mice of both genotypes (see also S1 Table for detailed statistical analysis)." (PMID 31206517, 2019).
colitis (continued). "Although a direct link to epithelial dysfunction has not been made to the colitis phenotype, these data suggest that C3H/HeJBir mice exhibit defects in TLR5-dependent host-microflora interactions, resulting in increased T cell responses to bacterial antigens (i.e., flagellin)." (PMID 24062746, 2013). "Indeed, we used fecal Lcn-2 as a means to distinguish colitic and non-colitic toll-like receptor 5 (TLR5) deficient mice, thus enabling us to monitor the intestinal microbiota as colitis developed." (PMID 22957064, 2012). "In addition, we have never observed spontaneous colitis in our TLR5−/− mouse colony." (PMID 23977202, 2013). "Thus, epithelial TLR5 activation may exert a protective role in the gut, whereas breach of this barrier during inflammatory conditions such as seen in IBD could lead to an exaggerated response to flagellin, similar as seen in dextran-sodium sulphate induced colitis in mice." (PMID 22279566, 2012).
metabolic syndrome (60 papers, 2010 to 2025). A cluster of metabolic risk factors for CARDIOVASCULAR DISEASES and TYPE 2 DIABETES MELLITUS. "For instance, TLR5-deficient mice exhibit increased fat deposition, systemic inflammation, and disrupted lipid metabolism, mirroring the features of metabolic syndrome in humans." (PMID 40444793, 2025). "Alterations in TLR5 sensing of the gut microbiome have been linked to the development of metabolic syndrome in TLR5−/− mice and disrupted gut microbiota composition, hyperphagia, hyperlipidemia, hypertension, insulin resistance, and increased adiposity." (PMID 40558558, 2025). "The causative role of affected microbiota in the development of metabolic syndrome is confirmed by microbial transplantation from TLR5-deficient to wild-type mice." (PMID 37505311, 2024). "Toll-like receptor-5 deficient (TLR5KO) mice with metabolic syndrome had cartilage damage similar to WT mice, which was alleviated by antibiotics." (PMID 37180142, 2023). "Null or epithelial-specific deletion of TLR5 impaired pathogen clearing and increased the susceptibility to microbial-induced colitis and metabolic syndrome." (PMID 37191444, 2023). "TLR5-deficient mice showed features of metabolic syndrome, including hyperglycemia and insulin resistance, which were significantly correlated with the altered gut microbiota." (PMID 35655996, 2022). "In one relevant case, the loss of the bacterial flagellin sensor TLR5 in mice provoked multiple pathologies associated with metabolic syndrome, and also shifted the abundance of a suite of about 100 bacterial taxa in the enteric microbiome." (PMID 32174902, 2020). "For instance, when the microbiota of TLR5-deficient mice was transplanted into wild-type TLR5 mice, the alteration of the wild type mice’s gut bacterial composition led to the development of obesity, insulin resistance, and metabolic syndrome." (PMID 33304339, 2020). "TLR5-deficient mice fed a HFD also exhibit exacerbated metabolic syndromes, including hyperlipidemia, insulin resistance, and increased adiposity." (PMID 31582899, 2019). "In loss-of-function mouse models, TLR5-deficient mice show altered gut microbiota composition, low-grade inflammation, metabolic syndrome, and predisposition to the development of colitis." (PMID 31582899, 2019). "This is in contrast to a loss of TLR5 on mouse intestinal epithelial cells, which resulted in low-grade inflammation along with metabolic syndrome and an inability to clear pathobionts." (PMID 31830087, 2019). "Metabolic syndrome in TLR5-deficient mice is exacerbated by HFD, suggesting that TLR5 is responsible for the balance of microbiota." (PMID 31582899, 2019). "A previous study found that TLR5 deficient mice (TLR5KO1) had altered gut microbial composition which led to the development of metabolic syndrome including hyperlipidemia, hypertension, insulin resistance and increased adiposity." (PMID 26950299, 2016). "Tlr5-deficient mice exhibit hyperphagia and develop hallmark features of metabolic syndrome, including hyperlipidemia, hypertension, insulin resistance, and increased adiposity." (PMID 27105827, 2016). "A previous study reported that TLR5 deficient mice (TLR5KO1) had alterations in gut microbiota composition that resulted in metabolic syndrome including hyperlipidemia, hypertension, insulin resistance, and increased adiposity." (PMID 26950299, 2016). "The current study has generated a second colony of TLR5KO2 and was aimed to explore the mechanistic links between gut microbiome and metabolic syndrome in TLR5 deficient mice." (PMID 26950299, 2016). "A deficiency in TLR5 also results in microbiota alterations that induce metabolic syndrome conditions such as obesity, insulin resistance and dyslipidemia." (PMID 26793178, 2015).
metabolic syndrome (continued). "For example, in mice, deficiency of Toll-like receptor 5 (TLR-5), an innate immune sensor of flagellin, results in mice that mimic the symptoms of metabolic syndrome including hyperlipidemia, hypertension, and insulin resistance." (PMID 25763184, 2015). "Transfer of microbiota from TLR5-deficient mice to its wild-type germ-free counterpart resulted phenotypic manifestation of metabolic syndrome." (PMID 24778627, 2014). "In addition, transferring gut microbiota from TLR5-deficient mice to WT germ-free mice confers the features of metabolic syndrome to recipients." (PMID 31582899, 2019). "Interestingly, the transfer of intestinal microbiota from TLR5-deficient mice to germ-free mice led to metabolic syndrome." (PMID 31205450, 2019). "The features of metabolic syndrome, including obesity, hyperlipidemia, hyperglycemia, and insulin resistance, were expressed in the recipients when an altered gut microbiota of the TLR5-deficient mice was transplanted into the intestines of wild-type germ-free mice." (PMID 31635264, 2019). "When microbiota from mice with metabolic syndrome or mice genetically deficient in Toll-like receptor 5 was transferred to the germ-free wild-type mice, the wild-type mice exhibited metabolic syndrome including insulin resistance, obesity, dyslipidemia, and hypertension." (PMID 31236708, 2019). "Furthermore, transplantation of cecal content from TLR5-deficient mice into wild-type germ-free mice resulted in development of metabolic syndrome." (PMID 27869680, 2016). "Results suggest that lower abundance of Bacteroides might be associated with higher risk of metabolic syndrome, even if this decrement is unrelated to TLR5 deficiency." (PMID 26950299, 2016). "Furthermore transplantation of microbiome from Tlr5-deficient mice to WT germ-free mice conferred many features of metabolic syndrome to the recipients." (PMID 27105827, 2016). "TLR5-deficient mice showed many features of metabolic syndrome together with gut dysbiosis." (PMID 27869680, 2016). "For example, deficiency in T-bet (Tbx2) promotes a colitogenic microbial population and ulcerative colitis, while deficiency in Toll-like receptor 5 (TLR5) alters the abundance of microbiota at species level leading to features characteristic of metabolic syndrome." (PMID 22723961, 2012). "Moreover, germ-free mice transplanted with microbiota from the TLR5-deficient mice showed various symptoms of metabolic syndrome such as obesity, insulin resistance, hyperglycemia, and elevated levels of pro-inflammatory cytokines, which were characteristic features of the TLR5-deficient mice." (PMID 37191444, 2023). "Importantly, transplantation of the gut microbiota from TLR5-deficient mice caused metabolic syndrome in wild-type germ-free mice, suggesting that the crosstalk between TLR5 and the gut microbiota might play an important role in metabolic disease." (PMID 35242721, 2022). "However, TRAF6 also interacts with proteins known to attenuate atherosclerotic lesion formation: recently it could be shown, that TLR5- deficient mice develop a metabolic syndrome." (PMID 20644648, 2010). "They utilized Toll-like receptor-5 deficient (TLR5KO) mice, which exhibit altered gut microbiota, to induce metabolic syndrome, and administered chronic antibiotics to TLR5KO mice to prevent metabolic syndrome (TLR5KOΔMicrobiota)." (PMID 39656496, 2024). "Unexpectedly, although long-term (6 months) supplementation of inulin (7.5%) improves metabolic syndrome in toll-like receptor 5 (TLR5)-knockout mice, many of these mice develop icteric hepatocellular carcinoma (HCC)." (PMID 33292701, 2020). "Knock out of TLR5 in mice led to the development of metabolic syndrome, which correlated with changes in the gut microbiota." (PMID 33178196, 2020). "TLR5 knock out in intestinal epithelial cells induced low grade inflammation and metabolic syndrome, which was reversed by antibiotics, implying a connection with the gut microbiota." (PMID 33178196, 2020).
metabolic syndrome (continued). "Transfer of feces from TLR5 knockout mice to wild type mice conferred many features of the metabolic syndrome." (PMID 33178196, 2020). "Toll-like receptor 5 (TLR5) expressed by the gut mucosa was suggested to play a role in metabolic syndrome." (PMID 27869680, 2016). "In contrast, an obvious metabolic syndrome and the presence of colitis and significant increases in the levels of IL-1β within their colons was confirmed in the same TLR5−/− mouse housed in different facilities." (PMID 25897427, 2015). "Moreover, the transfer of gut microbial communities from TLR5 knockout mice to wild-type (WT) germ-free mice results in the onset of metabolic syndrome." (PMID 39936163, 2025). "Thus, an interplay between the gut microbiome and TLR5 likely contributes to the pathophysiology of metabolic syndrome." (PMID 39936163, 2025). "The authors used germ-free and conventional Toll-like receptor 5 (TLR5) deficient (T5KO) mice, which are prone to develop microbiota-dependent metabolic syndrome, to first show that the T5KO mice displayed elevated hepatic neutral lipid content, depending on the presence of gut microbiota." (PMID 36902288, 2023). "In particular, TLR5 knockout mice develop metabolic syndrome compared to wild control mice." (PMID 35269587, 2022). "Firstly, they tried to examine whether inulin has a mitigating effect towards metabolic syndrome in Toll-like receptor 5 (TLR5) knockout mice." (PMID 34489956, 2021). "The research team initially attempted to examine whether inulin mitigates metabolic syndrome in Toll-like receptor 5 (TLR5) knockout mice." (PMID 32514151, 2020). "Another important role in the development of a metabolic syndrome has been demonstrated for the pattern recognition receptor such as the toll-like receptor 5 (TLR5), a component of the innate immune system expressed in the gut mucosa and one that helps defend against infection." (PMID 31205450, 2019). "Furthermore, TLR5-deficient mice are prone to develop spontaneous intestinal inflammation, and intestinal TLR5 signaling was demonstrated to be crucial for preventing gut inflammation and metabolic syndrome in mice." (PMID 31206517, 2019). "This assumption is strongly supported by the recent finding that toll like receptor 5 (TLR5) deficient mice, which exhibit a ~3-fold higher bacterial load and are prone to develop microbiota-dependent metabolic syndrome have increased hepatic SCD1 expression and oleic acid (FA18:1 n-9) levels." (PMID 30218046, 2018). "We conclude that an altered composition of the microbiota in a given environment can result in metabolic syndrome, but it is not a consequence of TLR5 deficiency per se." (PMID 26950299, 2016). "TLR5 deficient mice did not manifest metabolic abnormalities related to the metabolic syndrome compared with littermate controls maintained on normal chow or after feeding a high fat diet." (PMID 26950299, 2016). "For instance, we and others have not observed any evidence of intestinal inflammation, metabolic syndrome or measurable bacterial translocation across the mucosal barrier in tumor-bearing mice housed in our facilities, including TLR5-deficient animals." (PMID 25897427, 2015). "Several studies demonstrated that inactivation of TLR5 determines dysbiosis characterized by altered abundances of more that 100 phylotypes and a bloom in Enterobacteriaceae, especially E. coli, thus leading to spontaneous colitis and metabolic syndrome including insulin resistance." (PMID 37505311, 2024). "Likewise, TLR5 has not been directly linked to hypertension but has been linked to metabolic syndrome, of which hypertension is one of the distinguishing factors." (PMID 35269587, 2022). "Dysregulation of TLR5 signalling can contribute to chronic inflammation in conditions such as IBD and metabolic syndrome." (PMID 40444793, 2025).
metabolic syndrome (continued). "Through the method of bioinformatics, we finally obtained 10 hub genes in atherosclerosis and metabolic syndrome, and selected 3 of the most significant genes (CX3CR1, IL32, TLR5) for blood PCR verification." (PMID 39095691, 2024). "Additionally, a few studies reported that TLR5 may influence metabolic cascades in vivo; TLR5-KO mice, or impaired flagellin recognition, resulted in metabolic syndrome, changes in the composition of the intestinal microflora, impaired fat metabolism, and inflammation." (PMID 34948270, 2021). "The lack of metabolic syndrome traits in TLR5KO2 mice, led us to the hypothesis that different gut microbial compositions could explain the lack of a metabolic syndrome phenotype in the current experiments in contrast to results previously reported in TLR5 deficient mice." (PMID 26950299, 2016). "Another study indicates that even in the absence of the TLR5 gene, environmental factors can significantly influence the gut microbiome profile, thereby affecting metabolic syndrome outcomes." (PMID 38167804, 2024). "Mice lacking TLR5 showed alterations in the bowel flora, exhibiting symptoms such as metabolic syndrome and increased adiposity." (PMID 36428390, 2022). "The second most cited article was “Metabolic syndrome and altered gut microbiota in mice lacking Toll-like receptor 5”, published in the journal Science in 2010." (PMID 36683688, 2022). "published a paper in Science titled “Metabolic syndrome and altered gut microbiota in mice lacking Toll-like receptor 5”, which was the first to reveal that the GM participates in the development of metabolic diseases." (PMID 36683688, 2022). "Intriguingly, mice lacking TLR5, the receptor for bacterial flagellin, developed metabolic syndrome, and their gut microbiota was altered." (PMID 32218248, 2020). "For example, mice lacking TLR5 develop dysbiosis followed by metabolic syndrome (Tilg and Kaser 2009; Tremaroli and Bäckhed 2012)." (PMID 30460516, 2019). "Relative to similarly maintained WT mice, mice lacking TLR5 (T5KO) did not display low-grade intestinal inflammation nor metabolic syndrome under ASF conditions." (PMID 29617463, 2018). "Furthermore, in toll-like receptor 5 knockout (TLR5−/−) mice, metabolic syndrome was induced by altered gut microbiota with hyperphagic traits." (PMID 22383967, 2012). "As B420 decreased TLR5 gene expression in intestinal epithelial cells, it would be of great interest to study whether downregulation of TLR signaling and subsequent suppression of inflammation comprise one of the mechanisms by which beneficial microbes may reduce metabolic syndrome and obesity." (PMID 32218248, 2020).